APC (APC regulator of Wnt signaling pathway)
Diseases named in the same sentence as APC in open-access papers (continued):
Sharing a sentence is not in itself a finding about the gene and the disease.
adenoma (continued). "The chromosomal instability (CIN) pathway is associated with mutations in the APC gene or loss of 5q (APC) and mutations in the KRAS gene during progression of normal epithelium to early adenoma." (PMID 19678923, 2009). "When considering each gene separately, only APC displayed a significant difference between small and large adenomas (P = .014 in haplotypic analysis and P = .07 in genotypic analysis)." (PMID 19888426, 2009). "The APC gene is defined as a gatekeeper in the adenoma-carcinoma sequence theory of colorectal carcinogenesis because APC alterations, such as mutations and loss of heterozygosity, occur at an early stage of colorectal carcinogenesis." (PMID 16451736, 2006). "The overall adenoma and CRC risk as well as cases divided based on APC truncation mutation status, were assessed according to several smoking parameters." (PMID 16545110, 2006). "When dividing the adenoma case group based on APC truncational status "ever smoked" was significanly associated with APC - adenomas only, OR = 3.97.57 (CI 1.26–12.51)." (PMID 16545110, 2006). "Gene profiles of three adenomas and corresponding normal epithelial tissue from an FAP patient (case 640) with an APC germline mutation (n." (PMID 15982419, 2005). "Detection of PSG9 expression in adenomas, and at higher levels in FAP cases, indicates that germline APC mutations and defects in Wnt signalling modulate PSG9 expression." (PMID 15982419, 2005). "The most common fate switch that we were able to detect correlates with a down regulation of the APC gene and transformation into an adenoma-like phenotype." (PMID 15656904, 2005). "High levels and early deregulation of PSG9 in adenomas, as well as normal mucosa in some FAP cases, indicates the potent role of APC germline mutations that are often found in these cases." (PMID 15982419, 2005). "In short, there is an adenoma-like phenotype that fits with this genotype and this fits well with what is known about the function of the APC protein." (PMID 15656904, 2005). "Nonsteroidal anti-inflammatory drugs appear to inhibit the initial stages of the adenoma–carcinoma sequence, suggesting a link to the APC/β-catenin/TCF pathway (Wnt-signalling pathway)." (PMID 14710233, 2004). "Reports from Western countries indicate that pathogenic APC variants are found in 60%–70% of patients who have ≥ 100 adenomas; however, pathogenic variants of APC, biallelic MUTYH are observed in only 10%, 7% of those who have 20–99 adenomas, respectively." (PMID 41214301, 2026). "Genetic testing for APC may be selected in cases where FAP is strongly suspected based on adenoma density, the presence of extracolonic manifestations, or family history." (PMID 41214301, 2026). "All gastric-type adenocarcinomas had GNAS mutations as well as adenomas, while APC mutations were absent in intestinal-type adenocarcinomas and present in most adenomas." (PMID 40463821, 2025). "A previous study on FAP tumors suggested that KRAS mutations were not necessary in APC-associated FAP adenomas, as codon 12 mutations are rarely (10%) observed." (PMID 41488735, 2025). "Lastly, Finegoldia has been associated with APC-mutated colorectal tumors, which typically originate from the adenoma-carcinoma sequence rather than the serrated pathway." (PMID 40230532, 2025). "Our results agree that preventing access to ASN in APC mutant cells – both at the adenoma and carcinoma stage – may be critical when targeting ASNS for CRC therapy." (PMID 39332495, 2024).
adenoma (continued). "Genomic analysis of APC-driven adenomas and adjacent mucosa of FAP patients revealed that the tissue adjacent to the adenoma site carries 23% of the somatic mutations and genomic variations in known cancer driver genes, which are often detected in adenomas (i.e., APC, K-RAS, FBXW7, TCFL2)." (PMID 39594797, 2024). "To summarize, it may be true that CRA first obtains driver mutations for the genes of the Wnt signaling pathway (mainly APC) in a typical adenoma–carcinoma sequence." (PMID 36734304, 2023). "Unlike CRCs arising through the adenoma–carcinoma pathway, APC-inactivating mutations are rarely shown in the serrated neoplasia pathway." (PMID 35457279, 2022). "Moreover, sulindac treatment is reported to result in reduced β-catenin expression and Wnt signaling in mouse and human APC-mutant adenomas." (PMID 36860494, 2022). "In most cases of the adenoma–carcinoma sequence, the development of aberrant crypt foci in the initial stages of CRC development involves unregulated activation of the Wnt pathway via an inactivating APC mutation." (PMID 35975243, 2022). "Therefore, we propose to trace the spread of APC-mutant cells using a similar strategy to assess the effect of low-dose lithium on stem cell competition and number of adenomas in FAP patients." (PMID 35962368, 2022). "When a somatic pathogenic variant inactivates the wild-type parental allele, the lack of a functional APC protein results in the formation of hundreds to thousands of small adenomas, one or more of which will eventually undergo a malignant transformation." (PMID 36497357, 2022). "It is unclear whether APC I1307K is related to a higher risk for adenoma formation or the conversion from benign polyps to malignant polyps; however, compared to FAP, APC I1307K has lower penetrance, and the protein remains functional." (PMID 36497357, 2022). "Conversely, the high APC mutation rate in adenoma is evidence that small intestinal adenoma is unlikely to progress to adenocarcinoma, and that the adenoma-carcinoma sequence is not the main pathway of carcinogenesis of SBA." (PMID 35778698, 2022). "By contrast, MMR-P adenomas had a higher frequency of APC and CTNNB1 somatic mutations, but no RNF43 somatic mutations." (PMID 33923068, 2021). "For a long time, sporadic CRC has been perceived as a homogenous condition that occurs with the adenoma-carcinoma phenotype, which is caused by many genetic alterations of CRC key genes, such as KRAS, tumor suppressor protein (TP) 53, and APC Regulator Of WNT Signaling Pathway (APC)." (PMID 34299137, 2021). "APC deletion in LGR5+ colonic crypt base SCs induce the rapid transformation into adenomas: Aberrant WNT activity in the LGR5+ SC compartment might be responsible for the tumor-initiating process." (PMID 33562604, 2021). "In particular, MMR-D adenomas were characterized by RNF43 frameshift somatic mutations in mononucleotide repeats, frequently associated with insertions or deletions of three-repeat sequences in the APC gene." (PMID 33923068, 2021).
adenoma (continued). "ISC-specific deletion of both adenomatous polyposis coli (APC) alleles using either Bmi1-, CD133-, or LGR5-Cre recombinase mice leads to a rapid full adenoma formation, while a similar APC deletion in late progenitors or differentiated cells only results in sporadic and slow-developing adenoma." (PMID 33916891, 2021). "In addition, the fraction of indels among all somatic APC variants (90%) and the fraction of APC indels in repetitive sequences was significantly higher in the MSH3-deficient adenomas." (PMID 34843512, 2021). "Serrated adenocarcinomas, which account for 20–30% of CRC, follow an alternative pathway independent of APC mutations, in which serrated polyps replace traditional adenoma as the CRC precursor lesion." (PMID 34359960, 2021). "It has been reported that adenoma-carcinoma sequence usually does not result in the development of small-bowel cancers, instead the low frequency of APC gene mutations is responsible for their development." (PMID 34014970, 2021). "While variants in established cancer driver genes were identified in several of the present MSH3-deficient adenomas, each of the known more specific drivers of colorectal tumourigenesis (KRAS, FBWX7) was affected in only a single adenoma with the exception of APC." (PMID 34843512, 2021). "For years, the consensus was that APC mutations alone were responsible for the initiation of adenomas, but whole-genome sequencing of adenomas from FAP patients has implicated other non-Wnt genes." (PMID 33987182, 2021). "Similarly, PUMA loss facilitates CRC progression as PUMA KO mice develop more adenomas in both the APC Min/+ and inflammation-driven tumor models." (PMID 32335811, 2020). "It has been previously reported that APC loss in the intestine does require loss of p21 to generate adenomas and does not induce senescence." (PMID 32384699, 2020). "On the other hand, biofilms have also been detected in familial adenomatous polyposis patients who have inherited a mutation in the APC gene and are highly prone to CRC due to the development of polyps and adenoma formation as the early stage of the “adenoma-carcinoma sequence”." (PMID 32823729, 2020). "Inactivation of APC through mutations or loss of heterozygosity leads to aberrant activation of Wnt signalling, but even in the presence of dysfunctional APC, some degree of regulation of Wnt pathway activity is maintained to optimally enable adenoma formation." (PMID 32647253, 2020). "Sekine and colleagues found MMR deficient adenomas without APC mutations, which implies that MMR deficiency can occur during adenoma formation." (PMID 32847083, 2020). "One model hypothesizes that, initially, an adenoma forms through the usual mechanisms (WNT inactivation and biallelic APC loss), and then MMR deficiency occurs, prompting the transition to CRC." (PMID 32847083, 2020). "APC contributes to adenoma formation but some of its roles remain to elucidate." (PMID 32258104, 2020).
adenoma (continued). "Treatment with ABT-199 while intestinal stem cells are undergoing APC deletion and hence transformation strongly impairs adenoma outgrowth, which suggests that BCL-2 is a potential target for CRC chemoprevention in patients with high risk conditions such as familial adenomatous polyposis." (PMID 32335811, 2020). "APC-deficient adenomas were previously shown to exhibit nondirected cell migration along the crypt-villus axis." (PMID 33105836, 2020). "Mutations within APC result in ineffective targeting of β-catenin for degradation and causes a constitutively active Wnt pathway which results in an expanding ISC compartment followed by adenoma formation." (PMID 30927915, 2019). "As it is well known, adenomas and tumors coming from MUTYH biallelic carriers show a deficiency in the 8-oxo-hidroxyguanine repair system, leading to an increase in the G > T mutation rate, frequently in APC and KRAS15." (PMID 31285513, 2019). "Although approximately 90% of CRCs harbor APC mutations as the initiating events leading to clonal expansion of colonic stem cells and adenoma formation, the dysregulation of β-catenin and RAS is not sufficient to generate the CRC phenotype." (PMID 31362761, 2019). "Thus, it is plausible that the increase of Pde4b transcript in the ApcMin/+ adenomas and surrounding mucosa is secondary to active WNT signaling in the setting of loss of APC." (PMID 30188895, 2018). "APC+/min mice spontaneously develop multiple adenomas in the small intestine but few in the colon." (PMID 30140377, 2018). "Additionally, we performed multiregional, targeted next-generation sequencing (NGS) of adenomas and unmasked extensive heterogeneity, affecting known drivers such as APC, KRAS and mismatch repair (MMR) genes." (PMID 30166531, 2018). "Finally, given the role of CX3CR1 in regulating intestinal inflammation, we compared the formation of small intestine adenomas in APC+/min-CX3CR1+/- and APC+/min-CX3CR1-/-." (PMID 30140377, 2018). "In addition, strong activation of Pak and Akt was observed in adenomas from CDX2;APC mice, compared to weak staining exhibited in adenomas from CDX2;APC;PID mice." (PMID 30150766, 2018). "Nevertheless, 1 of the 11 adenomas had higher mutant APC DNA than controls." (PMID 28088238, 2017). "Further, niclosamide attenuates TCF/LEF transcriptional activity induced by APC mutants, and oral administration of niclosamide significantly suppresses adenoma formation in an APC-MIN model, of clinical relevance for familial adenomatosis polyposis (FAP) patients." (PMID 28418862, 2017). "A recent study reported an APC‐mutated pig, which yielded multiple adenomas in the colon; however, none developed into carcinomas." (PMID 28881081, 2017). "The inactivation of APC through promoter hypermethylation in adenoma and CRC." (PMID 28515349, 2017). "Overall, we conclude that growing APC−/− adenomas induce elimination of nearby cells by apoptosis." (PMID 26853366, 2016). "One adenoma was found to have LOH for the APC gene and was copy number neutral." (PMID 26970738, 2016).
adenoma (continued). "Given that Hippo signaling has been implicated in cell competition in developing tissues and that Wnt signaling induces YAP/TAZ activation in mammals, we investigated whether Yki is active in APC−/− adenomas and whether it plays a role in cell competition." (PMID 26853366, 2016). "Hyper-activation of JNK was prominent both inside APC−/− adenomas and in surrounding tissue." (PMID 26853366, 2016). "Epithelial mini-guts grown from adenomatous polyposis coli (APC)—mutant adenoma cells display the same symmetric shape, which is not surprising, because APC loss leads to constitutive Wnt pathway activation." (PMID 29056739, 2016). "We next tested the relevance of JNK activation to APC−/− adenoma growth and cell competition." (PMID 26853366, 2016). "Comparison of the mutational spectrums in our cohort to a set of 20 commonly mutated genes characterized in the TCGA CRC carcinoma cohort indicates that APC mutations are found in both tubular adenoma (MDA49ad-TA) and sessile serrated adenoma (MDA51ad-SSA) adenomas." (PMID 27100181, 2016). "Importantly, inducible expression of either Puc or JNKDN specifically in the host tissue severely reduced growth of APC−/− adenomas." (PMID 26853366, 2016). "We next wondered which pathways are involved in APC−/− adenoma expansion." (PMID 26853366, 2016). "In contrast to conventional adenoma, mutations in APC are an exception rather than the rule in the developmental pathway of serrated adenoma driven by BRAF." (PMID 26299805, 2015). "There are multiple lines of evidence that serrated adenomas are initiated via activating mutations in the EGFR-RAS-RAF signaling axis without prior APC inactivation." (PMID 26299805, 2015). "Using the APCmin/+ mouse model to establish colon adenoma cultures as a basis for drug discovery studies is clinically relevant as it is a pure adenoma model with well-defined genetic etiology closely mimicking the truncation of the APC gene as observed in most sporadic human colon adenomas." (PMID 26087250, 2015). "This process can be reproduced in mouse models for CRC, where the conditional deletion of APC in the intestinal epithelium imposes a stem/progenitor-like phenotype, leading to massive crypt hyperproliferation and formation of benign tumors known as adenomas." (PMID 24516653, 2014). "A substantial proportion of nonpolypoid and polypoid adenomas lack APC mutations, APC methylation or chromosomal loss of the APC locus on chromosome 5q, suggesting the involvement of other Wnt-pathway genes." (PMID 24350795, 2013). "Recently, we found that nonpolypoid adenomas display less APC mutations and simultaneously more frequent chromosome 5q loss (locus of APC) compared to polypoid adenomas." (PMID 24350795, 2013). "The APC/β-catenin pathway seems to be not affected ruling out that RTC originates through the traditional adenoma–carcinoma pathogenetic pathway underlying most CRCs." (PMID 23425390, 2013). "One polypoid and one flat adenoma harbored a CTNNB1 mutation, both at the same nucleotide position c.134C>T (p.S45F) and both adenomas contained no APC truncating mutation." (PMID 22848674, 2012).